PIK3CA (phosphatidylinositol-4,5-bisphosphate 3-kinase catalytic subunit alpha)
Diseases named in the same sentence as PIK3CA in open-access papers (continued):
Sharing a sentence is not in itself a finding about the gene and the disease.
angiosarcoma (24 papers, 2015 to 2025). A malignant tumor arising from the endothelial cells of the blood vessels. "Intriguingly, about 21% of all AS samples in the Angiosarcoma Project carried PIK3CA mutations which are targetable with FDA-approved drugs according to the OncoKB precision oncology database." (PMID 38914779, 2024). "Another study reported PIK3CA mutations at amino acid position 1,047 (H1047R, H1047L) in 45% (9/20) of hemangiosarcoma specimens of multiple breeds and 29.8% (14/47) of those of purebred dogs." (PMID 38033642, 2023). "Hemangiosarcoma shares its high rate of PIK3CA mutations with angiosarcoma, a rare tumor with poor survival rates in humans." (PMID 36658200, 2023). "One study reported that alpelisib exerts potent anticancer effects on canine PIK3CA-mutated hemangiosarcoma-derived cells." (PMID 38033642, 2023). "PIK3CA is the third most mutated gene across the tumor types, with the mutation especially common in hemangiosarcoma, mutated in 13% of the samples." (PMID 37414794, 2023). "In dogs, PIK3CA mutation was recently introduced as an actionable mutation in hemangiosarcoma with a low occurrence rate." (PMID 31842489, 2019). "One study found activating mutations in PIK3CA in 40% of tumors while other investigators describe elevated levels of phosphorylated S6 in 100% and phosphorylated 4EBP1 in 88% of angiosarcomas, both of which are downstream effectors of mTOR." (PMID 29872503, 2018). "In our dataset, PIK3CA mutations were present in 38 of 359 samples (10.6%); these rates are similar to a prior analysis that reported a rate of approximately 8.0% (53/665) across angiosarcomas." (PMID 41301029, 2025). "Additionally, BYL719 exerted a significant antitumor effect in canine hemangiosarcoma cell lines carrying PIK3CA mutations." (PMID 38807154, 2024). "However, a recent international cooperative project (Angiosarcoma Project) revealed that the PIK3CA activating mutation was one of the most frequently mutated genes in human AS." (PMID 38130992, 2023). "However, a recent large-scale analysis (Angiosarcoma Project) revealed that human AS also frequently has activating mutations in PIK3CA." (PMID 38130992, 2023). "PIK3CA mutations are commonly observed in two types of tumors, CMTs and hemangiosarcoma." (PMID 38033642, 2023). "PIK3CA mutation is also enriched in sarcoma including hemangiosarcoma (p = 4.70 × 10−5)." (PMID 37414794, 2023). "PIK3CA was the only gene with mutations in angiosarcomas located in different topographies." (PMID 37568749, 2023). "PIK3CA is another frequently mutated gene, mutated in 31% of hemangiosarcomas." (PMID 34344882, 2021). "Biased tumor occurrence by PIK3CA (A3140G) via H1047R, higher in CMTs than in other cancers such as hemangiosarcoma, might be related with the difference of somatic mutation profiles in tumor arising in men and woman." (PMID 31842489, 2019). "Canine spontaneous hemangiosarcoma is a useful model for angiosarcoma both in their histologies and common driver mutations, including NRAS, PLCG1, PIK3CA, and TP5321." (PMID 36658200, 2023). "In angiosarcomas, the most frequently mutated genes in all three cohorts were KDR, PIK3CA, and NF1, followed by KMT2D, NRAS, and PLCG1, which were among the top 10 genes in two of the three cohorts." (PMID 37568749, 2023).
angiosarcoma (continued). "Even in the injected Pten/Pik3ca mice, we observed at least one case of ovarian endometrioid hyperplasia (together with angiosarcoma detected in its uterus)." (PMID 35159108, 2022). "Five genes are expressed only in this type of sarcoma: PIK3CA, MDM2, HMGA2, EGFR, CDK, CDK4, while CDKN2A is implicated in angiosarcomas and undifferentiated pleomorphic sarcomas only." (PMID 34359782, 2021). "Angiosarcoma lesions exhibited significantly higher PIK3CA immunoreactivity than hemangiomas (χ2 = 20.97, P = .001)." (PMID 34397726, 2021). "Radiation- and lymphedema-associated angiosarcomas were associated with MYC gene amplification, whereas primary angiosarcomas of the breast showed a high rate of PIK3CA-activating mutations." (PMID 34545273, 2021). "The importance of the PIK3CA/AKT pathways in angiosarcoma is evident based on the conserved association between abnormalities in this pathway and the appearance of HSA or angiosarcoma across dogs, humans, and zebrafish, three evolutionarily distant species." (PMID 29061949, 2015). "PIK3CA mutations, ≥ 50% of which are H1047R/L, are also common, mutated at 12% (15/129) and 16% (6/37) in splenic and non-splenic hemangiosarcoma, respectively." (PMID 37414794, 2023). "These regions are highly conserved between the human and canine genomes, and are often mutated in canine hemangiosarcomas and mammary carcinomas; however PIK3CA was not mutated in our canine UC cohort, nor were genes encoding other components of PI3K." (PMID 37079639, 2023). "In almost all injected Pten/Pik3ca females, we observed aggressive angiosarcomas in their uteri after a very short latency; we also detected some angiosarcomas in the ovaries of the injected mice, possibly as a result of the metastatic spreading of angiosarcoma cells from the uterus to the ovary." (PMID 35159108, 2022). "Previous studies on the genomic landscape of angiosarcoma have described recurrent somatic mutations of angiogenic signaling pathway genes, including KDR, PTPRB, and PLCG114–18, as well as genes involved in oncogenic signaling pathways such as MAPK, PIK3CA/AKT/mTOR, and TP5319,20." (PMID 37106027, 2023). "We attribute the difference in the overall survival of PIK3CA and NRAS between dogs and humans to the high frequency of hemangiosarcoma analyzed in this study, representing 19% of studied dogs." (PMID 36658200, 2023).
Venous malformation (24 papers, 2016 to 2026). A vascular malformation resulting from a developmental error of venous tissue composed of dysmorphic channels lined by flattened endothelium and exhibiting slow turnover. "Further studies revealed somatic GoF TEK variants (mainly L914F) in ~50% sporadic venous malformations, and in PIK3CA (mainly hotspot variants E542K, E545K, and H1047R) in 20%." (PMID 41272322, 2026). "Among these, venous malformations (VMs) are predominantly caused by mutations in the TIE2 or PIK3CA genes, which disrupt endothelial cell morphogenesis and vessel maturation." (PMID 41725941, 2026). "While PIK3CA mutations are recognized as the second most frequent genetic alteration in sporadic venous malformations, the molecular landscape of FAVA remains comparatively understudied." (PMID 40989492, 2025). "Klippel-Trenaunay syndrome (KTS) is a rare congenital venous malformation, it had been found to be caused by mutations of the phosphatidylinositol 4, 5-diphosphate 3-kinase catalytic subunit alpha (PIK3CA) gene." (PMID 38363945, 2024). "Sporadic venous malformations are genetic conditions primarily caused by somatic gain-of-function mutation of PIK3CA or TEK, an endothelial transmembrane receptor signaling through PIK3CA." (PMID 38880808, 2024). "Here, we again confirmed that most venous malformations are caused by somatic mutations in PIK3CA and TEK, although a genotype–phenotype correlation is difficult to establish, since patients with the same mutation can manifest different kinds of malformations." (PMID 33105631, 2020). "Activating mutations in the TIE2 receptor or the downstream signal transducer PIK3CA [p110α catalytic subunit of phosphatidylinositide-3 kinase (PI3K)] cause human venous malformations (VMs) while loss-of-function TIE2 mutations result in glaucoma." (PMID 27941161, 2017). "Further research is required to delineate how PIK3CA dysregulation uniquely contributes to FAVA's distinct clinico-pathological features compared to conventional venous malformations." (PMID 40989492, 2025). "Specifically, PIK3CA-related venous malformations showed a mean reduction of 33.4% (SD, ± 22.1) from the baseline at 6 months, while TEK-related venous malformations demonstrated a mean reduction of 27.8% (SD, ±18.9)." (PMID 38880808, 2024). "Nearly half of sporadic venous malformations (VMs) bear activating TEK mutations, while most others express activating PIK3CA H1047R, or E452K or C420R mutations, in a mutually exclusive manner." (PMID 36353506, 2022). "As such, circulating metabolites could serve as potential biomarkers for monitoring disease progression in PIK3CA-capillary venous malformations." (PMID 38880808, 2024). "In addition, FN was reported to sensitize ECs for low levels of Ang1 and promote Tie receptor interactions with α5β1-integrin, whereas venous malformation-causing activating mutations in TIE2 and PIK3CA resulted in loss of FN production by ECs." (PMID 27941161, 2017). "However, in vivo data suggested that miransertib may be less effective than alpelisib in PIK3CA-related venous malformations." (PMID 41272322, 2026). "Miransertib is shown to inhibit PI3K signaling and decrease cell viability in patient-derived PIK3CA-mutant cells from venous malformations, but no trials specifically addressing the effect on LM are currently ongoing." (PMID 38488007, 2024). "The absence of the PIK3CA mutation, therefore, does not preclude the diagnosis of KTS since capillary malformation, soft tissue hypertrophy, and venous malformations are present in this child." (PMID 33492467, 2021).
cervical squamous cell carcinoma (23 papers, 2011 to 2025). A squamous cell carcinoma arising from the cervical epithelium. "Patients with PIK3CA mutation of cervical squamous cell carcinoma showed increased survival rate in comparison to those without PIK3CA mutation." (PMID 38774756, 2024). "PIK3CA mutations prevalence in TCGA cervical squamous cell carcinoma study is 27.1% (67 of 251 cases)." (PMID 33435133, 2021). "In another series of mostly squamous cervical cancers, early stage IB and II PIK3CA mutated cancers had worse survival than patients with same stages PIK3CA wild-type cancers." (PMID 33435133, 2021). "ERBB2 mutations concomitantly harbored PIK3CA or KRAS mutations were found in non-squamous cervical cancer." (PMID 32922530, 2020). "Another study conducted in Italy revealed a 5% prevalence of PIK3CA mutations among patient with cervical squamous cell carcinoma." (PMID 31350972, 2019). "In HPV-positive head and neck and cervical squamous cancers, mutations in PIK3CA are almost exclusively found in E542K (c.1624G > A) and E545K (1633G > A) corresponding to a C to T single base change at a TCW motif, indicative of APOBEC-induced mutagenesis." (PMID 28771191, 2017). "In a study by McIntyre and co-workers, about 20% of squamous cervical cancer patients showed a PIK3CA mutation and these patients had a better prognosis than those with wild-type tumours." (PMID 24642661, 2014). "In patients with squamous cell carcinoma of the cervix, the presence of PIK3CA mutations was associated with a significantly longer overall survival (median, 9.4 months) than the absence of PIK3CA mutations (median, 4.2 months; p = 0.019)." (PMID 25426553, 2014). "In general, patients with metastatic or recurrent squamous cell carcinoma of the cervix were significantly younger, and had a higher prevalence of PIK3CA mutations." (PMID 25426553, 2014). "In tumor types with more than 10 patients tested, PIK3CA mutations were most common in squamous cell cervical cancer, in 5 (36%) of 14 patients." (PMID 21829508, 2011). "For this purpose, we utilized two CC cell lines which are the first from adenocarcinoma (HeLa cells with PIK3CA wt) and the latter from cervical squamous cell carcinoma with mutations in PIK3CA, which are reported to be associated with an immunosuppressive microenvironment." (PMID 37384250, 2023). "In cervical squamous cell carcinomas, the commonly altered genes were PIK3CA (35.3%) and FBXW7 (17.6%), consistent with similar studies." (PMID 35267660, 2022). "Cervical squamous cell carcinoma was entirely HPV-associated and mutations occurred in PIK3CA (60%), as well as in uterine serous carcinoma (80%)." (PMID 36010253, 2022). "Amplifications of the locus of PIK3CA at chromosome arm 3q26 are the most common copy number alterations in squamous cervical cancers in TCGA." (PMID 33435133, 2021). "All three PIK3CA gene mutants were from patients with FIGO stage 3 cervical squamous cell carcinoma." (PMID 31350972, 2019). "In line with this hypothesis we proposed here, a supporting observation has been reported for cervical squamous cell carcinoma (CECC), showing that patients with PIK3CA-E545K mutations showed a partial response to treatment with PD-1 inhibitors." (PMID 38616230, 2024). "Therefore, in this study, we investigated the frequency of PIK3CA and MDM2 mutations in Filipino patients with cervical squamous cell carcinoma." (PMID 31350972, 2019). "For these studies, we selected HeLa (cervical adenocarcinoma derived cell line with PIK3CA-WT), SiHa (cervical squamous cell carcinoma cell line with PIK3CA-WT) and CaSki cells (a cervical squamous cell carcinoma cell line that is heterozygous for PIK3CA-E545K)." (PMID 27489350, 2016).
cervical squamous cell carcinoma (continued). "Twenty-eight formalin-fixed paraffin-embedded cervical squamous cell carcinoma and 16 non-malignant cervix tissue biopsies of Filipino patients were subjected to PIK3CA gene and MDM2 SNP309 (rs2279744) analysis." (PMID 31350972, 2019).
metastatic colorectal cancer (22 papers, 2009 to 2025). "This is difficult to test experimentally, but consistent with the finding that PIK3CA mutation is a source of acquired cetuximab resistance in metastatic colorectal cancer patients." (PMID 32119655, 2020). "For e.g., it has been used for detection of mutations in KRAS, BRAF and PIK3CA in metastatic colorectal cancer." (PMID 28095454, 2017). "A recent meta-analysis reported that PIK3CA exon 20 mutations are associated with a significantly shorter DFS in KRAS wild-type metastatic colorectal cancer patients treated with anti-EGFR antibody cetuximab." (PMID 25980437, 2015). "The PIK3CA mutation is seen in 15% of individuals with metastatic colorectal cancer (mCRC)." (PMID 37280524, 2023). "PIK3CA mutation was associated with lung metastases in metastatic colorectal cancer." (PMID 35795065, 2022). "Cell 2 presented a good initial response against EGFR inhibitors, but the occurrence of the two PIK3CA pathogenic variants could be translated into the later acquisition of resistance to treatment, as described in metastatic colorectal cancer." (PMID 33917394, 2021). "We assessed whether selection according to RAS/PIK3CA/BRAF mutational status could be beneficial for patients treated with bevacizumab as first-line treatment for metastatic colorectal cancer." (PMID 28068936, 2017). "However, it remains unknown whether RAS/PIK3CA/BRAF tumor mutations can predict the efficacy of bevacizumab in metastatic colorectal cancer." (PMID 28068936, 2017). "Findings reported in the literature support additional testing of BRAF, PTEN and PIK3CA before anti-EGFR treatment in metastatic colorectal cancer." (PMID 22272141, 2011). "We address the prognostic and predictive value of KRAS, PIK3CA and BRAF mutations for clinical outcomes in response to active agents in the treatment of metastatic colorectal cancer (mCRC)." (PMID 19603024, 2009). "Both PTEN and PIK3CA alterations were reported to have strong relationships with UCEC and COADREAD, and the loss of PTEN expression is also observed to be associated with PIK3CA mutations in metastatic colorectal cancer." (PMID 26148869, 2015). "Cetuximab is approved for the treatment of metastatic colorectal cancer but its response rate in KRAS, BRAF, NRAS and PIK3CA exon 20 quadruple wild-type tumors accounts for only 41%, leaving a high percentage of non-responders." (PMID 28032592, 2017).